LACC1 (laccase domain containing 1)
Description:
Purine nucleoside enzyme that catalyzes the phosphorolysis of adenosine, guanosine and inosine nucleosides, yielding D-ribose 1-phosphate and the respective free bases, adenine, guanine and hypoxanthine. Also catalyzes the phosphorolysis of S-methyl-5'-thioadenosine into adenine and S-methyl-5-thio-alpha-D-ribose 1-phosphate. Also has adenosine deaminase activity. Acts as a regulator of innate immunity in macrophages by modulating the purine nucleotide metabolism, thereby regulating the metabolic function and bioenergetic state of macrophages. Enables a purine nucleotide cycle between adenosine and inosine monophosphate and adenylosuccinate that prevents cytoplasmic acidification and balances the cytoplasmic-mitochondrial redox interface. The purine nucleotide cycle consumes aspartate and releases fumarate in a manner involving fatty acid oxidation and ATP-citrate lyase activity. Participates in pattern recognition receptor (PRR)-induced cytokines in macrophages: associates with the NOD2-signaling complex and promotes optimal NOD2-induced signaling, cytokine secretion and bacterial clearance. Localizes to the endoplasmic reticulum upon PRR stimulation of macrophages and associates with endoplasmic reticulum-stress sensors, promoting the endoplasmic reticulum unfolded protein response (UPR). Component of L-arginine metabolism in activated macrophages supporting anti-inflammatory and antibacterial macrophage effector functions. Cleaves L-citrulline, a product of L-arginine metabolized via NOS2, to yield isocyanate, a reactive carbonyl species-like cytotoxin, and L-ornithine, a precursor in polyamine biosynthesis. Through L-ornithine controls cellular polyamine pools likely triggering polyamine-mediated proinflammatory cytokine suppression and autophagy stimulation. Directly interacts with components of autophagy machinery to regulate macrophage metabolism and bacterial phagocytosis. Acts downstream of the energy sensor AMP-activated protein kinase (AMPK) to promote autophagy associated to lipid droplets generation providing fatty acids for mitochondrial respiration. Does not show laccase activity.
Synonyms: C13orf31; FAMIN; FLJ38725; JUVAR
Tractability: PROTAC: ubiquitination databases record sites on it; its protein half-life has been measured.
Gene: Protein-coding gene on chromosome 13 (43,878,917 to 43,895,091, forward strand). Ensembl gene ENSG00000179630.
Subcellular location: Cytoplasm; Nucleus; Endoplasmic reticulum; Peroxisome
Gene Ontology:
Molecular function: adenosine deaminase activity; guanosine phosphorylase activity; oxidoreductase activity, acting on diphenols and related substances as donors, oxygen as acceptor; protein binding; purine-nucleoside phosphorylase activity; S-methyl-5-thioadenosine phosphorylase activity; copper ion binding
Biological process: nucleotide-binding oligomerization domain containing 2 signaling pathway; pattern recognition receptor signaling pathway; positive regulation of cytokine production involved in immune response; regulation of intracellular pH; regulation of inflammatory response; regulation of purine nucleotide metabolic process; regulation of defense response
Cellular component: endoplasmic reticulum; peroxisome; cytoplasm; nucleus
Genetic constraint (gnomAD): Loss-of-function variants: 24 observed, 29.14 expected, observed/expected ratio (o/e) 0.82, 90% interval 0.6 to 1.16. The upper end of that interval is the gene's LOEUF score, 1.16, which puts it in group 5 of 6, group 1 being the genes least tolerant of losing a copy. Missense variants: 393 observed, 488.99 expected, observed/expected ratio (o/e) 0.8, 90% interval 0.74 to 0.87. Synonymous variants: 153 observed, 164.09 expected, observed/expected ratio (o/e) 0.93, 90% interval 0.82 to 1.07.
Homologues: Orthologues: chimpanzee LACC1 (99% identical), macaque LACC1 (96% identical), pig LACC1 (87% identical), dog LACC1 (85% identical), rabbit LACC1 (85% identical), guinea pig LACC1 (81% identical), mouse Lacc1 (77% identical), rat Lacc1 (74% identical), tropical clawed frog lacc1 (57% identical), zebrafish lacc1 (42% identical).